MGAT5 (alpha-1,6-mannosylglycoprotein 6-beta-N-acetylglucosaminyltransferase)
Diseases named in the same sentence as MGAT5 in open-access papers (continued):
Sharing a sentence is not in itself a finding about the gene and the disease.
Autoimmunity (7 papers, 2015 to 2025). The occurrence of an immune reaction against the organism's own cells or tissues. "Mgat5 deficiency further contributes to aggravating autoimmunity by favoring the differentiation of the more proinflammatory TH1 and TH17 over TH2 CD4+ T cells." (PMID 38027254, 2023). "Abnormal N-glycan processing, particularly Mgat5 deficiency, has been associated with the development of autoimmunity due to effector T-cell hyper-activity." (PMID 28871258, 2017). "Similarly in humans, dysregulated Mgat5 activity has been linked to autoimmunity and hyperactivity of T cells." (PMID 38027254, 2023). "There is much evidence in the literature for the role of MGAT5 in autoimmunity, and in type 1 diabetes specifically." (PMID 36907892, 2023). "Taken together, these data provide strong evidence that Mgat5 plays a critical role in modulating T cell activation to ensure optimal T cell responses and to avoid exceeding the autoimmunity threshold." (PMID 38027254, 2023). "Deficiency of the N-glycan branching enzyme Mgat5 in mice promotes T cell activity, endocytosis of CTLA-4 and autoimmunity, including a spontaneous multiple sclerosis (MS)-like disease." (PMID 29487346, 2018). "MGAT5 is involved in negatively regulating T-cell activation and autoimmunity and T cells are the dominant lymphocyte population in canine blood." (PMID 26683458, 2015). "The up-regulated MGAT5 expression in both HT1 and HT2 groups vs. CTR and the higher content of complex-type N-glycans in HT1 suggest the importance of branched glycans in the CD25+ pool of CD4+ cells during the early stage of autoimmunization." (PMID 41030447, 2025).
glioma (7 papers, 2019 to 2024). A benign or malignant brain and spinal cord tumor that arises from glial cells (astrocytes, oligodendrocytes, ependymal cells). "Our results showed that blocking N-glycan biosynthesis by TM, SW or MGAT5 silencing caused a diminution of Slex in high-grade glioma cells." (PMID 33447350, 2020). "MGAT5 silencing reduced terminal SLeX expression in N-glycans, thus changing adhesion and migration properties in high-grade glioma cells." (PMID 39728102, 2024). "Another study using solution electrospun nanofiber scaffolds with a higher stiffness, of up to 166 kPa, demonstrated increased migration of glioma stem cells depending on multibranched N-glycans metabolized by MGAT5." (PMID 34680293, 2021). "It has been shown that increased expression of MGAT5, which mediates N-glycosylation of receptor protein tyrosine phosphatase type μ (RPTPμ) with β1,6-GlcNAc-branched N-glycans, reduces its activity, thereby increasing the invasiveness of glioma cells." (PMID 39728102, 2024). "In addition, TSA treatment of this low-grade glioma cell line accounted for a significant increase in the transcription rate of MGAT5 and FUT3/7/9." (PMID 33447350, 2020). "Moreover, we report an association of complex multi-antennary N-glycans presenting β1,6-GlcNAc branches with the high-grade glioma cells, which also overexpressed the gene responsible for these assemblies, MGAT5." (PMID 33447350, 2020). "In addition, downmodulation of N-glycosylation by treatment with the inhibitors Tunicamycin/Swainsonine or MGAT5 silencing decreased SLex expression, adhesion and migration in high-grade glioma cells." (PMID 33447350, 2020). "Besides, in accordance with the abundance of β1,6-GlcNAc branching, these cells overexpressed the related gene MGAT5 in comparison with low-grade glioma cell lines." (PMID 33447350, 2020). "In order to evaluate if Lewis glycans were part of N-glycans, we treated the high-grade glioma cell line LN229 with N-glycosylation inhibitors, Tunicamycin (TM) and Swainsonine (SW), and with a specific small interfering RNA (siRNA) targeting MGAT5." (PMID 33447350, 2020).
ovarian carcinoma (6 papers, 2014 to 2025). A malignant neoplasm originating from the surface ovarian epithelium. "In ovarian cancer, upregulation of MGAT5 could also exacerbate resistance to anti-PD-L1 immunotherapy by catalyzing branched N-glycans, which enhanced its binding with PD-1 on CD8+ T cells." (PMID 40873563, 2025). "Notably, decreased MGAT3 expression and increased MGAT5 expression may be concurrent phenomenon that both contribute to increasedβ1,6 GlcNAc branching in highly metastatic ovarian cancer." (PMID 24516574, 2014). "Survival analysis of available datasets showed that MGAT5 expression did not significantly correlate with progression free survival and overall survival of patients with ovarian cancer or recurrence free survival of patients with TNBC." (PMID 33579350, 2021).
glioblastoma (5 papers, 2018 to 2024). The most malignant astrocytic tumor (WHO grade IV). "Our findings are in line with previously reported results that show the overexpression of MGAT5 in a panel of glioblastoma cell lines and staining of β1,6-GlcNAc branching with the lectin PHA-L in glioblastoma specimens." (PMID 33447350, 2020). "Thus, the expression of MGAT5, which catalyzes the formation of β1,6-GlcNAc-branched N-glycans, acts as a key player in ensuring migration in glioblastoma stem cells." (PMID 39728102, 2024). "Thus MGAT5 N-glycan branching is critically involved in glioblastoma mechanosensing and regulation of stiffness dependent cell morphology and motility." (PMID 33894774, 2021).
lung carcinoma (5 papers, 2014 to 2022). "In addition, Elek and colleagues illustrated that MGAT5-rs34944508 was significantly correlated with lung cancer risk." (PMID 33879098, 2021). "Previous studies have reported that some glycosyltransferases and glycosidases within TGF-β pathway are tightly related to phosphorylation of TGF-β receptors, such as fucosyltransferase 8 (FUT8) in lung cancer and sialylated N-acetylglucosaminyl-transferase V (MGAT5, 37) in CRC." (PMID 35680565, 2022). "MGAT5 reduced radiosensitivity and increased malignancy in lung cancer cells." (PMID 34356834, 2021). "In lung cancer cells, TGF-β induced EMT through non-muscle myosin II-A/ JNK/ P38/PI3K axis, resulting in a concomitant up-regulation of MGAT5 and down-regulation of MGAT3." (PMID 34356834, 2021).
multiple sclerosis (4 papers, 2018 to 2025). A progressive autoimmune disorder affecting the central nervous system resulting in demyelination. "A genome wide association study (GWAS) identified two SNPs in MGAT5 associated with disease severity in individuals with multiple sclerosis (MS), an immune system disease that attacks the protective myelin sheath surrounding neurons." (PMID 35563467, 2022). "Evaluation of MGAT5 expression and its β1,6-GlcNAc branched glycan products has been well described in human multiple sclerosis (MS) and experimental autoimmune encephalitis (EAE) in mice." (PMID 41030447, 2025). "At the genetic level, several MGAT5 single-nucleotide polymorphisms (SNPs), associated with reduced expression of the MGAT5 enzyme, have been found to correlate with pathological changes in T cell glycosylation in chronic diseases such as IBD, COPD, and multiple sclerosis (MS)." (PMID 35833138, 2022). "To examine this with respect to MGAT5, we analyzed 111 NPC1 patients for two MGAT5 SNPs associated with multiple sclerosis; however, we did not identify an association with NPC1 phenotypic severity." (PMID 35563467, 2022).
colitis (3 papers, 2020 to 2025). Inflammation of the colon. "To further test this hypothesis, we metabolically supplemented colitis-susceptible Mgat5−/− mice with GlcNAc before disease induction." (PMID 39918275, 2025). "Furthermore, MGAT5 KO has been associated with inflammatory diseases such as colitis, which also correlates with increased expression of NKG2DLs and thereby increased immune activation." (PMID 32849657, 2020). "An extensive characterization of the different immune subsets in intestinal mucosa was performed at baseline and after colitis induction, comparing Mgat5WT and Mgat5−/− mice." (PMID 39918275, 2025). "A similar profile was also found in Mgat5−/− mice after DSS-induced colitis." (PMID 39918275, 2025). "Thus, AOM/DSS model was performed in both Mgat5 KO mice and WT mice (with a normal N-glycosylation pathway) and multiple euthanasia timepoints were defined to analyze different stages of carcinogenesis, from colitis to dysplasia and cancer." (PMID 40087977, 2025).
colorectal cancer (3 papers, 2017 to 2024). A primary or metastatic malignant neoplasm that affects the colon or rectum. "Further, additional work has demonstrated MGAT5-mediated branched N-glycans are an immune checkpoint in colorectal cancer and are overexpressed during colorectal cancer carcinogenesis." (PMID 38273829, 2023). "Mgat5 glycans affect sensitivity to TNF-α–mediated cell death in lung and colorectal cancer cells." (PMID 38912584, 2024). "The increased sensitivity found in the LLC and colorectal cancer lines confirms that the function of Mgat5 in limiting the response of cells to TNF-α is not restricted to PDAC." (PMID 38912584, 2024).
inflammatory bowel disease (3 papers, 2018 to 2023). A spectrum of small and large bowel inflammatory diseases of unknown etiology. "Additionally, in Inflammatory Bowel Disease (IBD), it was also demonstrated that lamina propria T lymphocytes from ulcerative colitis (UC) patients exhibited a deficiency in β1,6-GlcNAc branching N-glycans due to decreased levels of MGAT5 gene expression." (PMID 30538706, 2018).
liver cancer (3 papers, 2014 to 2023). An epithelial or non-epithelial malignant neoplasm that arises from the liver. "Future studies should investigate the exact roles of MGAT3 and MGAT5 in the context of each type of liver cancer." (PMID 36890858, 2023). "For example, IGF2BP1 facilitated hthe stemness of liver cancer cells by enhancing mannoside acetylglucosaminyltransferase 5 (MGAT5) mRNA stability via m6A modification." (PMID 37370759, 2023).
nasopharyngeal carcinoma (3 papers, 2013 to 2024). A carcinoma arising from the nasopharyngeal epithelium. "Decreased expression of Bcl-2 following downregulation of Mgat5 has also been observed in nasopharyngeal carcinoma." (PMID 38912584, 2024).
neuroblastoma (3 papers, 2013 to 2020). Neuroblastoma (NB) is the most common solid, extracranial childhood tumor. "It has been shown that higher expression of the Mgat5 gene (encodes GnT-V) was associated with a more favorable prognosis in neuroblastoma." (PMID 29902282, 2018). "On the contrary, it was reported that increased Mgat5 (encodes GnT-V, an enzyme that produces β1,6-branched N-glycans) expression levels are associated with favorable neuroblastomas since decreases in Mgat5 expression levels were associated with more invasive tumor stages." (PMID 29902282, 2018).
pancreatic adenocarcinoma (3 papers, 2024 to 2025). "The knocking out MGAT5 or using 2-Deoxy-D-glucose in pancreatic adenocarcinoma inhibited the synthesis of branching N-glycans, resulting in enhanced activity and reduced exhaustion of CAR-T cells." (PMID 40760673, 2025).
ulcerative colitis (3 papers, 2021 to 2023). An inflammatory bowel disease involving the mucosal surface of the large intestine and rectum. "Moreover, genetic variants of the MGAT5 glycogene were described in ulcerative colitis patients and found to be associated with low transcription amounts of MGAT5, and agalactosylation of circulating IgGs, often associated with proinflammatory phenotypes." (PMID 37407365, 2023). "Data from two independent European IBD cohorts with ulcerative colitis (UC) have shown that variants on the MGAT5 gene, coding for N-acetylglucosaminyltransferase [GnT]-V enzyme affect the glycosylation pattern in T cells and IgG." (PMID 33941843, 2021).
depression (2 papers, 2017 to 2020). "Thus, SLC35A3 may be associated with depression via its actions on Mgat5." (PMID 28596527, 2017).
liver disease (2 papers, 2021 to 2022). "It is possible that the reduced weight is secondary to the more severe liver disease phenotype in the Mgat5−/−:Npc1−/− mice." (PMID 35563467, 2022). "We also demonstrated that in the liver from patients with different liver diseases, fibrosis progression correlates with the increase in Mgat-5 expression." (PMID 34064584, 2021). "However, Mgat5−/−:Npc1−/− had significantly higher levels of AST levels compared to Mgat5+/+:Npc1−/− mice, suggestive of a more severe liver disease phenotype." (PMID 35563467, 2022). "Both Mgat5−/−:Npc1−/− (n = 9) and Mgat5+/+:Npc1−/− (n = 5) mice exhibited generally elevated levels of these enzymes in their serum compared to the control mice (Mgat5+/+:Npc1+/+ (n = 8), and Mgat5−/−:Npc1+/+ (n = 10)), suggestive of liver disease in both groups at this age." (PMID 35563467, 2022). "In the absence of MGAT5, Npc1−/− mice exhibited earlier liver disease, a 1–2 week earlier progression of the disease phenotype, and increased beam walk latency." (PMID 35563467, 2022).
liver fibrosis (2 papers, 2021). "The effect of MGAT5 was evident also on the promotion of physiological EMT in a mouse model of liver fibrosis in which KO of MGAT5 reduced the process." (PMID 34356834, 2021). "Inhibition of MGAT5 expression, which blocks the generation of branched N-glycans, profoundly suppressed TGF-β-induced EMT mediated by binding of galectin-3 to MGAT5-modified N-glycans in hepatocytes and prevented liver fibrosis." (PMID 32583064, 2021).
mastitis (2 papers, 2023 to 2025). Inflammation of breast tissue during lactation or postpartum due to an obstructed duct or infection. "Additionally, MGAT5 has been associated with mastitis resistance." (PMID 40362136, 2025). "In this study, the ZRANB3, PIAS1, ACTR3, LPCAT2, MGAT5, and SLC37A2 genes in Xinjiang brown cattle, which are associated with mastitis resistance, were identified using a GWAS." (PMID 37372369, 2023). "These six genes (ZRANB3, PIAS1, ACTR3, LPCAT2, MGAT5, and SLC37A2) are all potentially associated with mastitis resistance." (PMID 37372369, 2023).
oral cancer (2 papers, 2013 to 2020). "For example, in oral carcinoma, upregulation of MGAT5 plays an active role in disease progression." (PMID 32352014, 2020).
pancreatic carcinoma (2 papers, 2020 to 2024). "The N-glycosyltransferase Mgat5 inhibits the ability of a T cell to kill its target, rendering immunotherapy less effective in a mouse model of pancreatic cancer." (PMID 38912584, 2024). "The alterations in gene expression and glycome levels are also consistent with a previous report showing the increased degree of MGAT3 and MGAT5 activities in the tissues of pancreatic carcinoma patients." (PMID 32232009, 2020). "To determine whether pancreatic cancer is sensitive to pharmacological inhibition of Mgat5, we treated mice bearing T cell–inflamed 2838c3 WT tumors with either swainsonine (1 mg/kg or 4 mg/kg) or vehicle control for 2 weeks." (PMID 38912584, 2024).
prostate carcinoma (2 papers, 2015 to 2019). A carcinoma that arises from epithelial cells of the prostate gland. "However, in later stages of prostate cancer, expression and formation of Mgat5/galectin-3 lattices may stimulate and elevate the expression of CAV1 through phosphorylation, resulting in up-regulated CAV1 expression in advanced prostate tumours." (PMID 26112043, 2015). "In early stages of prostate cancer, the expression of CAV1 is lost and the expression of Mgat5 and galectin-3 is at low levels." (PMID 26112043, 2015).
schizophrenia (2 papers, 2006 to 2020). A major psychotic disorder characterized by abnormalities in the perception or expression of reality. "Interestingly, another protein N-glycosylation pathway gene, MGAT5 (Mannoside acetylglucosaminyltransferase 5) at chromosome band 22q21, was also found to be disrupted by an unbalanced translocation breakpoint in a schizophrenia case." (PMID 16859551, 2006).
bile duct carcinoma (1 paper, 2016). "Our group independently found that the Ets-1 oncogenic transcription factor directly transactivates the MGAT5 promoter in human bile duct carcinoma cells and that the Ets-1 levels were highly correlated with the levels of GnT-V expression in various cancer cell lines." (PMID 27136596, 2016).
brain cancer (1 paper, 2022). A primary or metastatic malignant neoplasm affecting the brain. "GnT-V, a glycosyltransferase encoded by the gene MGAT5, was shown to be increased in brain cancer, contributing to a decrease in cellular adhesion and promoting metastasis." (PMID 35159390, 2022).
choriocarcinoma (1 paper, 2025). An aggressive malignant tumor arising from trophoblastic cells. "Previous studies have demonstrated that lysosomal membrane protein LAMP2, glycosylated by MGAT5, promotes choriocarcinoma progression by enhancing N-glycan–mediated cell adhesion through galectin interactions." (PMID 41061966, 2025).
colorectal tumors (1 paper, 2023). "MMP13 or (Collagenase-3) and MGAT5 play known roles in tumor metastasis and invasion in gastrointestinal tract tumors, head and neck squamous carcinomas esophageal cancer and colorectal tumors." (PMID 37256183, 2023).
demyelinating disease (1 paper, 2011). A broad group of disorders that affect the myelin sheaths that cover the neurons. "Here we explore whether Mgat5 deficiency in myelin-reactive T cells is sufficient to promote demyelinating disease." (PMID 22389815, 2011). "These T-cell-specific phenotypes are consistent with enhanced susceptibility to demyelinating disease in Mgat5-deficient mice; however, they do not exclude disease promotion by non-T cells." (PMID 22389815, 2011).
experimental autoimmune encephalomyelitis (1 paper, 2011). An autoimmune demyelinating disease of the central nervous system that is produced experimentally in animals by the injection of homogenized brain or spinal cord in Freund's adjuvant. "Mgat5, a gene in the Asn (N-) linked protein glycosylation pathway, associates with MS severity and negatively regulates experimental autoimmune encephalomyelitis (EAE) and spontaneous inflammatory demyelination in mice." (PMID 22389815, 2011). "Mice deficient in Mgat5 display enhanced delayed-type hypersensitivity, spontaneous kidney autoimmunity, and increased susceptibility to experimental autoimmune encephalomyelitis (EAE)." (PMID 22389815, 2011).
fibrosis (1 paper, 2021). the formation of excess fibrous connective tissue in an organ or tissue in a reparative or reactive process. "We observed a significantly upregulated expression of MGAT5 in HBV- and NAFLD-associated fibrosis in patients with advanced disease (advanced fibrosis) compared to those at the initial stage of the disease or without fibrosis." (PMID 34064584, 2021).
growth deficiency (1 paper, 2024). "Collectively, these results suggest that immune-mediated clearance is responsible for the growth deficiency associated with Mgat5 loss, with nonimmune factors also playing a role." (PMID 38912584, 2024).
immunodeficiencies (1 paper, 2024). "NOD/SCID mice contain an array of immunodeficiencies that could have contributed to the rescue of Mgat5-KO tumor growth." (PMID 38912584, 2024).
Insulin resistance (1 paper, 2023). Increased resistance towards insulin, that is, diminished effectiveness of insulin in reducing blood glucose levels. "In vivo, Mgat5 deficient mice are resistant to weight gain on a high-fat diet with improved insulin sensitivity, whereas transgenic mice overexpressing Mgat5 in the liver, display obesity, steatosis, and insulin resistance." (PMID 37918808, 2023).
pancreatic ductal adenocarcinoma (1 paper, 2024). An infiltrating adenocarcinoma that arises from the epithelial cells of the pancreas. "Using a panel of murine pancreatic ductal adenocarcinoma (PDAC) clonal cell lines that recapitulate the immune heterogeneity of PDAC, we found that Mgat5 is required for tumor growth in vivo but not in vitro." (PMID 38912584, 2024).